CHEK2 (checkpoint kinase 2)
Diseases named in the same sentence as CHEK2 in open-access papers (continued):
Sharing a sentence is not in itself a finding about the gene and the disease.
breast cancer (continued). "Additionally, results from breast cancer case-control cohorts, such as BRIDGES and CARRIERS, suggest that not all CHEK2 variants confer equivalent risk." (PMID 39642869, 2024). "However, familial breast cancer was not as strong of a predictor of ATM or CHEK2 PV status among unaffected women." (PMID 37084156, 2023). "In addition, the last V5 version of BOADICEA incorporates the effects of pathogenic variants (PVs), not only in BRCA1 and BRCA2 genes, but also in PALB2, CHEK2, ATM and BARD1 for the breast cancer model and RAD51D, RAD51C and BRIP1 for the ovarian cancer model." (PMID 35886069, 2022). "Since participant A did not have any known relative with breast cancer, she and her close relatives were not recommended breast cancer surveillance and no predictive CHEK2 testing could be performed in her family." (PMID 34711244, 2021). "CHEK2: After BRCA1 and BRCA2, this was the first breast cancer moderate risk gene to be identified after observing a common deletion (1100delC) in non-BRCA breast cancer families." (PMID 34439109, 2021). "Comparison between PRR14 genetically altered and unaltered breast cancer samples shows that CHEK2 transcription is reduced (P = 0.014) in PRR14 genetically altered breast cancer samples, accompanied by not significantly less protein and significantly less activated form p-CHEK2 (T68) (P = 0.038)." (PMID 32541902, 2020). "However, the frequencies of these twenty mutant alleles of BRCA1/2, CHEK2, PALB2, NBN, and RECQL have not been measured in a large series of early-onset breast cancer patients from Poland." (PMID 32824581, 2020). "Indeed, it has been reported that the BRIP1 and RAD51 pathogenic variants confer at least a 6-fold increased risk for OC, but not for breast cancer, in contrast to the NBN and CHEK2 genes." (PMID 30441849, 2018). "In the present study, we screened a large population based sample, including 3748 non-cancer individuals and 7081 incident cancer cases (breast cancer, n = 1717; prostate cancer n = 2501, lung cancer n = 1331 and colorectal cancer n = 1532), for the distribution of CHEK2 R95*." (PMID 27708748, 2016). "The CHEK2-Breast Cancer Consortium reported a frequency of 5.1% for the CHEK2*1100delC variant in familial breast cancer cases who tested negative for BRCA1 and BRCA2 (Breast cancer 2, early onset) mutations, as opposed to 1.1% of carriers in the control population." (PMID 21569354, 2011). "Only one CHEK2 1100delC carrier did not have a family history of breast cancer." (PMID 17705858, 2007). "We examined the mutation frequency of BRCA1, BRCA2, CHEK2 and ATM in women who had developed a second primary breast tumour at least 1 year after a first breast cancer diagnosed before the age of 50 years, with or without RT for their first breast cancer." (PMID 17428320, 2007).
breast cancer (continued). "Importantly, in that same study we also found that the proportion of breast cancer patients receiving radiotherapy did not significantly differ between the CHEK2*1100delC carriers and non-carriers." (PMID 17428320, 2007). "All of the tagSNPs in the CHEK2 and ERBB2 genes and two of the tagSNPs in the ATM gene were not only genotyped in breast cancer cases and controls who participated through blood sample donation, but were also genotyped in breast cancer cases who participated through tissue sample donation." (PMID 17132159, 2006). "The number of women in the present study with a first-degree family history of breast cancer who tested negative for BRCA1/BRCA2 mutations (71 cases, 27 controls) does not offer adequate power to detect differences in the frequency of CHEK2 variants within this stratification." (PMID 15535844, 2004). "The CHEK2 variants included 2 patients with CHEK2 del5395, 1 patient with CHEK2 1100delc and 1 patient with CHEK 2 IVS2 + 1G > A. Additionally, one patient in the matched group of 3,884 healthy controls without breast cancer was found to harbor a variant in both CHEK2 and BRCA1." (PMID 33507482, 2021). "Within Asia, a South Korean study of 235 patients at high-risk for hereditary breast cancer and were confirmed not to have a BRCA1/2 mutation were tested with massively parallel sequencing, and 3.6% were found to have pathogenic germline mutations in CHEK2, PALB2, MRE11 and RAD50." (PMID 30093976, 2018). "BOADICEA V5’s newest version includes the effects of pathogenic variants (PVs), not restricted to BRCA1 and BRCA2 genes but also in PALB2, CHEK2, ATM, and BARD1 for the breast cancer model and RAD51D, RAD51C, and BRIP1 for the ovarian cancer model." (PMID 39590369, 2024). "This is consistent with previous reports in breast cancer and cell line experiments where Signature 3 was only detected for BRCA1/2, PALB2 and RAD51C genes but not ATM or CHEK2." (PMID 33917078, 2021). "In conclusion, in contrast to BRCA1/2 breast cancers, no apparent predominant specific CNA profile nor robust gene expression profile for CHEK2*1100delC breast cancers was found." (PMID 26553136, 2015). "CHEK2 1100delC, RAD50, and NBS1 do not appear to correlate with breast cancer in the Chinese population and should not be considered in genetic testing." (PMID 23318652, 2013). "To date, no studies have been conducted on breast cancer-driven genes such as ATM, PALB2, CHEK2, and XRCC2 reported from the Khyber Pakhtunkhwa region or Pashtun ethnicity and their potential associations with the various clinicopathologic and hormonal characteristics." (PMID 38784039, 2024). "Statistical adjustments for personal history, type and age of family history, and ancestry using a multivariable logistic regression model further support previous findings that age at breast cancer diagnosis is not a strong predictor of carrying ATM, CHEK2, or PALB2 PVs." (PMID 37084156, 2023).
breast cancer (continued). "Also, gene expression analysis identified a very small number of differentially expressed genes between the CHEK2*1100delC and BRCAX breast cancers, of which, except for possibly CENPJ, none seem to have a putative role in CHEK2 related tumorigenesis based on what is known in literature." (PMID 26553136, 2015).
ovarian carcinoma (163 papers, 2004 to 2025). A malignant neoplasm originating from the surface ovarian epithelium. "Recently, 21 founder and recurrent mutations in BRCA1/2, PALB2, RAD51C, and CHEK2 genes have been analyzed in a large Polish case-control study including 2270 ovarian cancer patients and 1743 controls." (PMID 35313928, 2022). "Mutations in BRCA1 and PALB2 genes were significantly associated with the high risk of ovarian cancer G1, while CHEK2 missense mutation (c.470T>C) was associated with 2-times elevated risk of BOT." (PMID 35313928, 2022). "The CHEK2 missense mutation (c.470T>C) was previously analyzed in another study of 539 ovarian cystadenomas, 122borderline ovarian tumors, and 447 ovarian cancer cases, including 88 low-grade (G1) tumors." (PMID 35313928, 2022). "The aim of the study was to analyze the prevalence and association of recurrent founder germline mutations in BRCA1, BRCA2, RAD51C, PALB2, and CHEK2 genes with ovarian cancer risk among unselected patients in the Polish population." (PMID 33670479, 2021). "Genotyping of 21 mutations in BRCA1, BRCA2, RAD51C, PALB2, and CHEK2 genes was performed for all 2270 ovarian cancer patients and 1743 healthy controls." (PMID 33670479, 2021). "Several founder mutations in the BRCA1, BRCA2, PALB2, RAD51C, and CHEK2 genes are associated with breast and ovarian cancer." (PMID 33670479, 2021). "The aim of the study was to analyze the frequency and magnitude of association of 21 recurrent founder germline mutations in BRCA1, BRCA2, PALB2, RAD51C, and CHEK2 genes with ovarian cancer risk among unselected patients in Poland." (PMID 33670479, 2021). "Among carriers of CHEK2 protein truncating mutations, 50% of patients survived 5 years from ovarian cancer diagnosis, but all died within 10 years." (PMID 33670479, 2021). "In one patient (ID3) with a pathogenic SDHB variant, we found an additional pathogenic germline variant in CHEK2 (c.1100delC, p.(Thr367fs)) that is known to be associated with hereditary breast and ovarian cancer." (PMID 31212687, 2019). "In this study, we have genotyped 68 MBC patients for the known breast or ovarian cancer associated mutations in the Finnish population in CHEK2, PALB2, RAD51C, RAD51D, and FANCM genes." (PMID 28874143, 2017). "Nevertheless, these analyses were mainly focused on some specific variants of CHEK2 (del1100C, A252G, and I157T); therefore, mutations of other regions of CHEK2 and their association with ovarian cancer pathogenesis still need to be investigated in detail." (PMID 26075229, 2015). "Our findings suggests that CHEK2 germ line mutations play a negligible role in early-onset and familial breast/ovarian cancer in Pakistan and imply that CHEK2 mutation screening of high-risk patients is not warranted in this population." (PMID 23806170, 2013). "Our contribution to this area of investigation was to establish relevance in the BRCA1/2-negative high-risk breast/ovarian cancer Pakistani population by assessing the prevalence of CHEK2 mutations." (PMID 23806170, 2013). "An additional group of 229 high-risk BRCA1/2-negative breast/ovarian cancer patients (Group 2) were screened for the identified CHEK2 mutations." (PMID 23806170, 2013). "Although the numbers are small, our data suggests that further investigation into the association between the CHEK2 1100delC mutation and ovarian cancer risk is warranted." (PMID 15535844, 2004). "Both females with CHEK2 1100delC and I157T CHEK2 GPVs may be receiving risk-reducing surgeries to prevent both breast and ovarian cancer, which may again be care beyond that currently recommended." (PMID 39062660, 2024). "However, there are few studies on the association of CHEK2 mutations and age at the onset of ovarian cancer." (PMID 38817903, 2024).
ovarian carcinoma (continued). "The role of CHEK2 mutations in ovarian cancer cancerogenesis is well known." (PMID 34207450, 2021). "However, in esophageal squamous cell carcinomas and some ovarian cancers, higher expression of CHEK2 is associated with favorable response to cisplatin-based therapy." (PMID 34645978, 2021). "Mutations in RAD51C, PALB2, and CHEK2 genes were previously analyzed in ovarian cancers." (PMID 33670479, 2021). "Excluding CHEK2, a pathogenic mutation was present in 262 of 2095 cases of ovarian cancer (12.5%)." (PMID 33670479, 2021). "Moreover, the association between CHEK2 and ovarian cancer can be a serious problem with reproductive health." (PMID 32570972, 2020). "Furthermore, several groups have previously analyzed the role of CHEK2 mutations in ovarian cancer cancerogenesis." (PMID 26075229, 2015). "Furthermore, we identified c.8187G>T as a characteristic mutation of BRCA2 in the Chinese population, and the CHEK2 mutation was significantly associated with the early onset of ovarian cancer, while the CDH1 and FAM175A mutations were more prevalent in Northeast China." (PMID 38817903, 2024). "In that study, the significant association of CHEK2 missense mutation (c.470T>C) with the risk of non-invasive tumors (OR = 1.7, p = 0.005 for ovarian cystadenoma and OR= 2.6, p = 0.002 for BOTs) and borderline significant correlation with low-grade ovarian cancer (OR=2.1, p = 0.04) were reported." (PMID 35313928, 2022). "BRCA1 and BRCA2 encode proteins involved in recombinational repair of damaged DNA and it has been found that mutations in other genes involved in the repair of DNA damage by homologous recombination, including e.g., RAD51C, RAD51D, BRIP1, PALB2, and CHEK2 may be associated with ovarian cancer risk." (PMID 33670479, 2021). "A study in Poland containing 2012 ovarian cancer patients showed that the average age of the ovarian cancer group with CHEK2 was 38 years, while the average age of the CHEK2-negative ovarian cancer group was 49 years." (PMID 38817903, 2024). "We identified significant high-frequency mutations in the ERCC4, CHEK2, and PDGFRA genes in young patients with ovarian cancer." (PMID 38817903, 2024). "PPM1D variants have been associated with predisposition to breast and ovarian cancers along with MUTYH and CHEK2." (PMID 36555431, 2022). "Consensus guidelines for hereditary breast and ovarian cancer include management recommendations for pathogenic/likely pathogenic (P/LP) variants in ATM, CHEK2, PALB2, and other DNA damage repair (DDR) genes beyond BRCA1 or BRCA2." (PMID 35626031, 2022). "Genotyping of 21 mutations in BRCA1, BRCA2, RAD51C, PALB2, and CHEK2 genes was performed for 102 BOT patients, 167 cases of ovarian cancer G1, and 1743 healthy controls." (PMID 35313928, 2022). "Women with disease-causing gene changes (faults/mutations) in BRCA1, BRCA2, PALB2, CHEK2 and ATM are at an increased risk of developing certain types of cancer—specifically breast (all genes) and epithelial ovarian cancer (only BRCA1, BRCA2, PALB2)." (PMID 35681696, 2022). "Prexasertib, a promising CHEK1 and CHEK2 inhibitor tested in ovarian cancer patients would be a candidate for treating CLL." (PMID 35301276, 2022).